PARP1 (poly(ADP-ribose) polymerase 1)
Diseases named in the same sentence as PARP1 in open-access papers (continued):
Sharing a sentence is not in itself a finding about the gene and the disease.
cancer (continued). "The findings of this study suggest that PARP‐1 rs1136410 C>T polymorphism has a board‐line significant relationship with overall cancer risk." (PMID 33108038, 2020). "Currently, specific inhibitors against BER proteins such as Polβ, PNKP, FEN1, Ligase IIIα, and PARP1/PARG have been developed either to sensitize several cancers or to form synthetic lethal partnerships with common cancer mutations." (PMID 33553154, 2020). "This phosphorylation causes reduced binding activity of PARP1 competitive inhibitors, which in turn develops the PARP1 inhibitor-resistance in cancer cells." (PMID 32405340, 2020). "The present work aims to fill this gap in the literature by presenting the latest updated meta‐analysis of the available evidence in elucidating the relationship of PARP‐1 rs1136410 T>C and the risk of cancer." (PMID 33108038, 2020). "Null significant association between PARP‐1 rs1136410 C>T and overall cancer risk was detected in their analysis." (PMID 33108038, 2020). "The inhibition of PARP-1 is helpful in the treatment of cancers because it causes accumulation of DNA damage and synthetic lethality of cancer cells presenting defects in homologous recombination (HR)-mediated DNA repair machinery." (PMID 32267490, 2020). "Due to the critical roles of PARP‐1 protein in cancer, the possible role of PARP‐1 gene SNPs in cancer susceptibility has evoked intensive investigation." (PMID 33108038, 2020). "For instance, cancer cell resistance to PARP inhibitors can emerge through the loss or mutations of PARP1 and lead to a decrease of PARP inhibitor binding." (PMID 32883316, 2020). "Normally, PARP1 is upregulated in breast, uterine, ovarian, lung, and skin cancers but is highly expressed in certain cancer types with BRCA1 mutations that display defects in homologous recombination (HR)." (PMID 33330383, 2020). "Inhibition of PARP-1 impairs the DNA damage repair and causes apoptosis of cancer cells, and therefore reduces the intensity of chemotherapy and eventually the damage to human body." (PMID 32373627, 2020). "The role of PARP1 in cancer management seems to be much more associated with its ability to mediate DNA repair than its ability to induce parthanatos." (PMID 33665167, 2020). "Overall, pooled data showed that the PARP‐1 rs1136410 C>T polymorphism was significantly but a border‐line associated with an increased risk of overall cancer (CC vs. TT/TC: OR = 1.11, 95% CI = 1.00‐1.24; C vs T: OR = 1.07, 95% CI = 1.01‐1.14)." (PMID 33108038, 2020). "PARP1 inhibitors are expected to serve as therapeutic agents for various cancers such as breast cancer susceptibility gene 1 (BRCA1)- and BRCA2-associated hereditary breast and ovarian cancers, prostate cancer, non-small cell lung cancer, and Ewing sarcoma." (PMID 32405340, 2020). "Polymorphisms in PARP1 have been reported to be associated with the risk of several kinds of cancers." (PMID 32355298, 2020). "Secondly, we showed that the observed aberrant FGFR1 and PARP1 expression was associated with cancer stem cell-like phenotype, regulated DNA repair, and modulated the response to therapy in PDAC cells." (PMID 32276472, 2020). "PARP1/2 inhibitors being superior to existing cancer treatment regimens for HR-deficient cancer patients, as clearly manifested in clinical trials, led to their approval for clinical use for the first time in 2014." (PMID 32784607, 2020). "Our meta‐analysis is the most updated and comprehensive study thus far to investigate the relationship between PARP‐1 gene rs1136410 C>T variant and predisposition to cancer." (PMID 33108038, 2020).
cancer (continued). "SNP rs1136410 C>T, the most studied polymorphism in PARP‐1 gene, is highly implicated in the susceptibility of cancer." (PMID 33108038, 2020). "The common concept in utilizing PARP inhibitors for cancer therapy is based on evidence associating PARP1 inhibition with the prevention of DNA break repair causing apoptotic cell death." (PMID 32575437, 2020). "Intervention with PARP-1 has been proved to be more sensitive to cancer cells carrying BRCA1/2 mutations." (PMID 32779949, 2020). "PARP-1 is an abundant and ubiquitous nuclear enzyme related to DNA repair; its overexpression is linked to the development of some types of cancer." (PMID 31850224, 2019). "The use of PARP1 inhibitors as monotherapies for patients with BRCA-mutated cancer demonstrates how effective synthetic-lethality screens can be for drug development." (PMID 31640753, 2019). "Other novel, highly scoring gene pair predictions that included cancer associated genes included PARP1 with PBRM1, BRCA2, ARID1A and APC as well as PIK3CA with MAP2K1, ABL1 and EGFR." (PMID 30995217, 2019). "Inhibition of PARP1 in cancer therapy is a strategy used in those types of cancers where DNA repair is defective causing an effect called “synthetic lethality”." (PMID 31105872, 2019). "PARP-1 inhibitors can be utilized not only as a single agent for the treatment of BRCA1- or BRCA2-deficient cancers, but in combination with DNA-damaging therapeutics (radiation or chemotherapy) to improve their potencies by blocking DNA-repairing process." (PMID 30427217, 2019). "A number of single nucleotide polymorphisms (SNPs) in the PARP1 gene are reported to be associated with the risk of several types of cancer." (PMID 31413734, 2019). "Of note, targeting mortalin and PARP1 by Mortaparib also caused decrease in BRCA1 that has earlier been shown to cause collateral lethality of cancer cells and increase in γH2AX protein." (PMID 31856867, 2019). "Olaparib, Niraparib, Rucaparib, Talazoparib and Veliparib are FDA approved drugs for PARP1 inhibition in BRCA1 mutated cancers." (PMID 31856867, 2019). "Use of PARP-1 inhibitors in breast cancer 1 (BRCA1) or breast cancer 2 (BRCA2) mutated tumors leads to synthetic lethality by making them highly sensitive to CDDP and other DNA damaging agents." (PMID 31303961, 2019). "RAD52 maintains residual HR in BRCA-deficient PARPi-treated cancer cells, so simultaneous targeting PARP1 and RAD52 represents an attractive therapeutic approach." (PMID 31615159, 2019). "For instance, PARP1 functions in DNA damage repair are the most attractive strategy to induce selective cell death in DNA damage repair-deficient cancers." (PMID 30991935, 2019). "We demonstrated increased survival of HMGA2 expressing cancer cells under DNA stress, despite the fact that increased PARP1 activity can potentially cause cell death through NAD+ depletion and energy failure." (PMID 30289618, 2019). "PARP1 is often enriched in cancer cells and its inhibition has been shown to cause cell death making it an attractive target for cancer treatment." (PMID 31856867, 2019). "Inhibition of PARP-1 accelerates the damage of injured DNA, which especially leads to synthetic lethality in DNA-repairing-deficient cancer cells, for example BRCA1/2-deficient cells." (PMID 30427217, 2019). "Olaparib, Simmiparib, Veliparib and MK4827 have been reported to cause N-terminal inhibition of PARP1 leading to growth arrest/apoptosis of cancer cells." (PMID 31856867, 2019). "The gene regulatory effects of PARP-1 have been linked to the control of inflammation, metabolism, circadian rhythms, and cancer." (PMID 30395643, 2018). "They find that TSP upregulation occurs via PARP1-mediated chromatin remodeling, leading to activation of multiple cancer-associated pathways." (PMID 30271949, 2018). "These alterations can decrease the BER pathway capacity and hence increase the cancer susceptibility in PARP1 Ala762 carriers." (PMID 30183716, 2018).
cancer (continued). "Pharmacological inhibition of PARP1 was first introduced in cancer therapy to exploit synthetic lethality of BRCA1-deficient breast tumors and is now widely tested in combination with DNA damaging chemotherapeutic drugs." (PMID 30356649, 2018). "A recent report also has shown that PARP1-mediated chemo-resistance is associated with the expression of snail, the master gene involved in the epithelial to mesenchymal transition of cancer cells." (PMID 29784019, 2018). "Change in amino acid results in reduced activity of PARP1 gene, which ultimately relates to increased risk of different cancers." (PMID 30183716, 2018). "Previous studies demonstrated that loss of some tumor suppressive miRNAs leads to PARP1 up-regulation in cancer, such as miR-216b, let-7, miR-345, and miR-221." (PMID 29776974, 2018). "Subsequently, PARP1 inhibitors induce apoptosis of cancer cells that have deficiency in key components of the HR pathway, which utilizes the sister chromatid as a template for a correct repairment of the DNA sequence." (PMID 29967475, 2018). "PARP1 overexpression was detectable in various cancer cell lines and was associated with malignant progression." (PMID 29343717, 2018). "Accordingly, inhibition of PARP1 preserves energy, and keeps PARP1 at relatively normal levels, subsequently causing the generation of apoptosis cancer cells which can be cleared by macrophages." (PMID 28991194, 2017). "To reveal the underlying mechanism of SLC6A9 downregulation in resistant cancer cells, a continuous complementary region was identified in the PARP-1 promoter sequence when we inspected the genomic sequence of SLC6A9." (PMID 28086241, 2017). "A well-known example of this is the inhibition of the DNA repair component PARP1 in the BRCA1-deficient cancers result in replication fork collapse and mitotic catastrophe." (PMID 28756516, 2017). "As to tumor progress, PARP-1 was revealed to be overexpressed in numerous malignant tumors and associated with invasiveness and poor prognosis." (PMID 29179487, 2017). "Its potent PARP1/2 inhibition can be effectively translated into its selective killing on HR-deficient cancers and synergistic sensitization of HR-proficient cancers to anticancer drugs." (PMID 27926532, 2017). "In the initial stage of BRCA1 mutation, cells are generally naïve and sensitive before they acquire multiple genetic mutations and eventually develop into cancer cells, which are resistant to PARP1 inhibition." (PMID 29069872, 2017). "The present study further revealed that cancer cell death was primarily caused by ATP exhaustion in excessive DNA repair with high PARP-1 activity." (PMID 28086241, 2017). "PARP1 inhibition in BRCA1-deficient cancers results in collapsed replication forks and genomic instability leading to mitotic catastrophe and ultimately cell death." (PMID 28756516, 2017). "In this situation, PARP1 inhibition stalls replication forks, which cannot be repaired because of the underlying defect in HR in these cancers." (PMID 28756516, 2017). "As a consequence, PARP1 inhibitors are today registered as monotherapy in cancers bearing DNA-repair deficiencies and the strong rational to combine selected cytotoxics (especially alkylators) with PARP1 inhibitors has to face the risk of myelotoxicity." (PMID 28454547, 2017). "Previous studies have shown that cancer cells deficient in DSB repair are sensitive to PARP1 inhibitors." (PMID 29348879, 2017). "It has been previously reported that high level of PARP1 expression is often associated with poor overall survival in cancer." (PMID 28654422, 2017).
cancer (continued). "The expression of PARP1 and γH2AX were significantly associated with shorter survival of various human malignant tumors." (PMID 27643881, 2016). "While disease-associated mutations in RAD51 are extremely rare, depletion by siRNA or miRNA induces a “BRCAness” phenotype and sensitizes cancer cells to DNA damaging agents such as cisplatin and PARP1 inhibitors similarly, to BRCA1 and BRCA2 mutations." (PMID 26910887, 2016). "Especially, when there are defects in DSB repair by mutation of BRCA1/2, inhibition of PARP1 results in un-repairable DNA DSBs and apoptosis of cancer cells." (PMID 27643881, 2016). "PARP1 inhibitors (PARPi) were found to be “synthetic lethal” in cancers deficient in BRCA1/2 with impaired homologous recombination." (PMID 26799421, 2016). "A weak, but significant association of high (3+) nuclear PARP1 expression was observed with BRCA1-mutated/-methylated cancers compared with wildtype TNBC specimens (50 % vs. 18 %, p = 0.016; n = 62)." (PMID 27756336, 2016). "For example, pioneering studies of SL partners in BRCA1 and BRCA2-deficient cancer cells identified PARP1 as a promising drug target." (PMID 27655641, 2016). "Inherent defects in the homologous recombination DNA repair pathway in BRCA-deficient tumors coupled with the inhibition of PARP1 lead to a synthetic lethality culminating in cancer cell death." (PMID 26354718, 2015). "These insights have prompted the search for cancer-associated mutations in HR genes, to be used for patient stratification for PARP1 inhibitors or other drugs that differentially affect HR-deficient cancers." (PMID 25852742, 2015). "PARP inhibition elicits anti-tumour activity in BRCA-mutant HR-deficient cancers, due to the dependency of these cancers on PARP1 activity in SSB repair to avoid replication-dependent accumulation of DSBs." (PMID 26505995, 2015). "Clearly, these observations indicate that there is a strong need to reliably identify cancers with defective HR repair, in order to stratify patient for therapies that target HR-deficient cancers, including PARP1 inhibitors." (PMID 25852742, 2015). "Pooling the data from 39 studies, we reconfirmed the function of PARP-1 Val762Ala in increased cancer risk among Asian populations." (PMID 24853559, 2014). "As so far, there were only two meta-analyses have being investigated the role of PARP1 Val762Ala polymorphism in overall cancer risk." (PMID 24489833, 2014). "For instance, only two studies have reported the combined effect of XRCC1 Arg194Trp and PARP-1 Val762Ala genotypes on the risk of cancer." (PMID 24853559, 2014). "Although the PARP-1 Val762Ala polymorphism and susceptibility to cancers have been discussed, all of the eligible studies have not been included, particularly case-control studies published in the past two years." (PMID 24853559, 2014). "Recently, significant work in the area of synthetic lethality has led to new approaches for the treatment of BRCA1/2-deficient cancers using high efficacy poly(ADP-ribose) polymerase 1 (PARP1) inhibitors (PARPi) with high efficiency." (PMID 24962108, 2014). "In conclusion, the present meta-analysis provided strong evidence of the association of PARP-1 Val762Ala with increased cancer risk among Asian populations." (PMID 24853559, 2014). "PARP-1 has been found to be overexpressed in a variety of cancers and its expression has been associated with overall prognosis in cancer." (PMID 24416253, 2014). "Overall, this updated meta-analysis with addition of fifteen latest published studies allowed us to provide a more precise relative risk estimate regarding the association between PARP1 Val762Ala polymorphism and cancer susceptibility." (PMID 24489833, 2014). "The present meta-analysis aimed to update previous meta-analyses and derive a reliable conclusion regarding the effect of the V762A polymorphism on the function of PARP-1 in cancer." (PMID 24853559, 2014).
cancer (continued). "Overall, in this updated meta-analysis investigating the association between PARP1 Val762Ala polymorphism and cancer risk, 43 studies with a total number of 17351 cases and 22401 controls were included." (PMID 24489833, 2014). "In the subgroup analysis of ethnicity, PARP-1 V762A was significantly associated with an increased risk of cancer in Asian populations in all of the genetic models (e.g., dominant model: OR = 1.17, 95% CI = 1.09–1.25)." (PMID 24853559, 2014). "Characteristics of the 43 studies included in the meta-analysis for an association between PARP1 Val762Ala polymorphism and risk of cancers." (PMID 24489833, 2014). "Numerous studies have examined the associations between PARP1 Val762Ala (rs1136410 T>C) polymorphism and cancer susceptibility; nevertheless, the findings from different research groups remain controversial." (PMID 24489833, 2014). "Considering gene-gene interaction analysis, we found a significant joint effect of ERCC1 –399Gln and PARP-1–762Ala on increased cancer risk in a homozygous genetic model." (PMID 24853559, 2014). "False-positive report probability values for associations between cancer risk and the frequency of genotypes of PARP1 gene." (PMID 24489833, 2014). "For example, EWS-Fli1 expression has been linked to sensitivity to PARP-1 inhibitors in a systematic identification of genomic markers of drug sensitivity in cancer cells." (PMID 23405229, 2013). "PARP-1 inhibitors have been shown to be effective in selectively inducing synthetic lethality in cancer cells, particularly in BRCA1- or BRCA2-deficient tumours." (PMID 23405229, 2013). "Is chronic activation of PARP-1 in highly oxidative environments responsible for the increased inflammation leading to genome instability and cancer, or are the DNA damages causing an upregulation of PARP-1?" (PMID 24202328, 2013). "Loss of PARP-1 activity not only decreases pro-tumor inflammation, but also inhibits two related hallmarks of cancer through anti-inflammatory mechanisms: proliferative signaling and metastasis." (PMID 24350055, 2013). "Perhaps the most well-known tumoricidal effects of PARP inhibitors are in BRCA-mutated cancers, which harbor DNA repair defects and become dependent on PARP-1-mediated repair for survival." (PMID 24350055, 2013). "The clinical and preclinical studies have also revealed other targets of PARPi in cancer therapies that are linked to various roles of their multifunctional target PARP-1 in following cellular processes." (PMID 24294592, 2013). "Of note, the SNP of PARP-1 Val762Ala (GTG/GCG) was associated with increased risk of various cancers." (PMID 22624032, 2012). "Studies have demonstrated that PARP-1 Val762Ala polymorphism is associated with an increased risk of carcinomas, including prostate, esophagus, lung, stomach, breast, and urinary bladder." (PMID 20196871, 2010). "The polymorphisms of PARP-1 have been associated with the risk of various carcinomas, including breast, lung, and prostate." (PMID 20196871, 2010). "To resolve these divergent observations, we determined PARP-1 polymorphisms, PARP-1 protein expression and activity in a panel of 19 solid and haematological, adult and paediatric human cancer cell lines." (PMID 19568233, 2009). "Thus, in the context of tumor growth suppression, the efficacy of JPI-547 in HRD cells was comparable to that of olaparib, as targeting PARP1/2 alone was sufficient to eliminate HR-deficient cancer cells." (PMID 40959288, 2025). "In addition to this, both mutations and loss of PARP1 have been detected in PARPi-resistant cancer cells." (PMID 39927794, 2025). "Furthermore, we suggest that an inhibitor demonstrating significant PARP1 trapping capability along with potent PARylation inhibition will be the most effective as a single agent for cancers characterised by HRR deficiency." (PMID 41459749, 2025).